DMAC1 (distal membrane arm assembly component 1)
Description:
Required for the assembly of the mitochondrial NADH:ubiquinone oxidoreductase complex (complex I). Involved in the assembly of the distal region of complex I.
Synonyms: C9orf123; TMEM261; MGC4730
Tractability: Antibody: UniProt predicts a signal peptide or a membrane-spanning region. PROTAC: ubiquitination databases record sites on it.
Gene: Protein-coding gene on chromosome 9 (7,796,500 to 7,888,380, reverse strand). Ensembl gene ENSG00000137038.
Subcellular location: Mitochondrion inner membrane
Pathways (Reactome):
Metabolism: Complex I biogenesis
Gene Ontology:
Biological process: mitochondrial respiratory chain complex I assembly
Cellular component: mitochondrial inner membrane; mitochondrion
Genetic constraint (gnomAD): Loss-of-function variants: 12 observed, 9.64 expected, observed/expected ratio (o/e) 1.24, 90% interval 0.79 to 1.84. That is too few expected variants to judge how well the gene tolerates losing a copy. Missense variants: 219 observed, 161.71 expected, observed/expected ratio (o/e) 1.35, 90% interval 1.21 to 1.51. Synonymous variants: 92 observed, 68.32 expected, observed/expected ratio (o/e) 1.35, 90% interval 1.14 to 1.6.
Homologues: Orthologues: chimpanzee DMAC1 (99% identical), macaque DMAC1 (72% identical), rabbit DMAC1 (71% identical), dog DMAC1 (66% identical), mouse Dmac1 (57% identical), pig DMAC1 (54% identical), guinea pig DMAC1 (52% identical), rat Dmac1 (47% identical).
Diseases named in the same sentence as DMAC1 in open-access papers:
DMAC1 is named in the same sentence as 7 diseases in open-access papers, as found by Europe PMC text mining. Sharing a sentence is not in itself a finding about the gene and the disease. The quoted sentences say what the papers report.
mitochondrial disease (1 paper, 2025). "Knockout of DMAC1 causes complex Iassembly defects, which are linked to mitochondrial diseases." (PMID 41523972, 2025).
DMAC1 also shares sentences with these, for which no sentence is quoted: breast carcinoma (2 papers); cancer (1); lung carcinoma (1); metastatic tumors (1); schizophrenia (1); tumor (1).